GLE1 (GLE1 RNA export mediator)
Description:
Required for the export of mRNAs containing poly(A) tails from the nucleus into the cytoplasm. May be involved in the terminal step of the mRNA transport through the nuclear pore complex (NPC).
Synonyms: hGLE1; GLE1L; CAAHC; CAAHD; LCCS; LCCS1
Tractability: Small molecule: a structure with a bound ligand is known. PROTAC: ubiquitination databases record sites on it; its protein half-life has been measured.
Gene: Protein-coding gene on chromosome 9 (128,504,655 to 128,543,874, forward strand). Ensembl gene ENSG00000119392.
Subcellular location: Nucleus; Cytoplasm; Cytoplasm (Isoform 1); Nucleus, nuclear pore complex
Subcellular location (Human Protein Atlas): Nuclear membrane; Cytosol; Nucleoli
Pathways (Reactome):
Metabolism of RNA: Transport of Mature mRNA derived from an Intron-Containing Transcript
Gene Ontology:
Molecular function: protein binding; inositol hexakisphosphate binding; phospholipid binding; translation initiation factor binding
Biological process: mRNA export from nucleus; nucleocytoplasmic transport; poly(A)+ mRNA export from nucleus
Cellular component: centriole; centrosome; ciliary basal body; cytoplasm; cytosol; extracellular region; membrane; nuclear envelope; nuclear membrane; nucleolus; nucleus; nuclear pore; nuclear pore cytoplasmic filaments
Genetic constraint (gnomAD): Loss-of-function variants: 50 observed, 57.38 expected, observed/expected ratio (o/e) 0.87, 90% interval 0.69 to 1.1. The upper end of that interval is the gene's LOEUF score, 1.1, which puts it in group 4 of 6, group 1 being the genes least tolerant of losing a copy. Missense variants: 497 observed, 609.41 expected, observed/expected ratio (o/e) 0.82, 90% interval 0.76 to 0.88. Synonymous variants: 199 observed, 234.73 expected, observed/expected ratio (o/e) 0.85, 90% interval 0.75 to 0.95.
Gene-disease validity (ClinGen):
ClinGen rates the evidence that GLE1 causes each of these diseases.
amyotrophic lateral sclerosis (autosomal dominant): Limited. Amyotrophic lateral sclerosis (ALS) is a neurodegenerative disease characterized by progressive muscular paralysis reflecting degeneration of motor neurons in the primary motor cortex, corticospinal tracts, brainstem and spinal cord.
Homologues: Orthologues: macaque GLE1 (97% identical), chimpanzee GLE1 (96% identical), pig GLE1 (89% identical), dog GLE1 (87% identical), rabbit GLE1 (85% identical), mouse Gle1 (83% identical), guinea pig GLE1 (79% identical), rat Gle1-ps1 (66% identical), rat Gle1l1 (64% identical), zebrafish gle1 (48% identical), tropical clawed frog gle1 (45% identical), Drosophila melanogaster Gle1 (22% identical).
Diseases named in the same sentence as GLE1 in open-access papers:
GLE1 is named in the same sentence as 18 diseases in open-access papers, as found by Europe PMC text mining. Sharing a sentence is not in itself a finding about the gene and the disease. The quoted sentences say what the papers report.
anterior horn cell disease (9 papers, 2014 to 2024). "Lethal congenital contracture syndrome and lethal arthrogryposis with anterior horn cell disease associated with GLE1 were first reported in FIN population." (PMID 38361118, 2024). "GLE1 was first identified as causative in a severe autosomal recessive lethal congenital contracture syndrome 1 and lethal arthrogryposis with anterior horn cell disease." (PMID 32616075, 2020). "Lastly, Gle1 mutations that are associated with motor neuron diseases possess severe thermostability defects, suggesting that nucleoporin misfolding contributes to disease." (PMID 29899397, 2018). "Mutations linked to motor neuron diseases cause decreased Gle1 thermostability, implicating nucleoporin misfolding as a disease determinant." (PMID 29899397, 2018). "Biochemical analyses of Gle1 variants associated with human disease suggest that nucleoporin stability is a contributing factor in motor neuron disease." (PMID 29899397, 2018). "For example, the mutation of the export factor GLE1 is linked to two motor neuron diseases: Lethal congenital contracture syndrome-1 and Lethal arthrogryposis with anterior horn cell disease." (PMID 26343730, 2015). "Interestingly, other Gle1 mutations found in LCCS-1 or LAAHD (lethal arthrogryposis with anterior horn cell disease), a related disease, lead to delocalization of Gle1 from NPCs." (PMID 25184662, 2014). "Mutation in the GLE1 gene (GLE1 RNA export mediator) leads to lethal congenital contracture syndrome type 1 (LCCS1) and congenital arthrogryposis with anterior horn cell disease (OMIM)." (PMID 39650934, 2024). "Worth special mention are EXOSC3 and GLE1, which are strong enhancers of C9ORF72 expansion toxicity and causative in a rare form of motor neuron disease." (PMID 32616075, 2020). "Mutations in Gle1 are associated with two genetic disorders: LCCS1 (lethal congenital contracture syndrome 1) and LAAHD (lethal arthrogryposis with anterior horn cell disease)." (PMID 33375634, 2020). "Specific mutations of Gle1 are associated with lethal contracture congenital syndrome 1 (LCCS1), lethal arthrogryposis with anterior horn cell disease (LAAHD), and ALS33,34." (PMID 29899397, 2018).
lethal congenital contracture syndrome 1 (6 papers, 2014 to 2025). "Mutations in Gle1 have been described in LCCS-1 (lethal congenital contracture syndrome 1), a genetic disease characterized by a complete fetal immobility in association with neuronal and muscular defects." (PMID 25184662, 2014). "GLE1 dysfunction has been associated with devastating diseases, including lethal congenital contracture syndrome 1(LCCS1), a rare disorder enriched in isolated populations." (PMID 40674274, 2025). "Lethal Congenital Contracture Syndrome 1 (LCCS1) is a severe autosomal recessive disorder caused by mutations in the GLE1 gene, located on chromosome 9q34.11." (PMID 39457470, 2024). "The misspliced GLE1 caused by single nucleotide substitution leads to the genetic disease, lethal congenital contracture syndrome 1 (LCCS1)." (PMID 29746542, 2018). "The changes partially mimic lethal congenital contracture syndrome 1 (LCCS1), which is an autosomal recessive disease causally linked to the GLE1 dysfunction." (PMID 40674274, 2025). "The mRNA export factor GLE1 protein plays critical yet enigmatic functions in RNA processing and has been linked with multiple developmental disorders, including lethal congenital contracture syndrome 1 (LCCS1)." (PMID 40674274, 2025). "The two AMC subtypes related to GLE1 are lethal congenital contracture syndrome 1 (LCCS1) and lethal arthrogryposis with anterior horn cell disease (LAAHD)." (PMID 39080077, 2024).
arthrogryposis (4 papers, 2014 to 2024). A rare, non-progressive congenital disorder characterized by multiple joint contractures which are present at birth. "This work also provides further insight into the mechanisms underlying human gle1 disease mutants found in prenatally lethal forms of arthrogryposis." (PMID 32981894, 2020). "Two families presenting with a current at-risk pregnancy were then studied prospectively, and a molecular genetic diagnosis was obtained in both families through the identification of GLE1 and RYR1 variants causing a severe form of fetal akinesia syndrome with arthrogryposis." (PMID 24961629, 2015).
amyotrophic lateral sclerosis (3 papers, 2018 to 2021). "GLE1 deleterious mutation was also found in amyotrophic lateral sclerosis (ALS) patients." (PMID 29746542, 2018).
arthrogryposis multiplex congenita (1 paper, 2024). Arthrogryposis multiplex congenita (AMC) is a group of disorders characterized by congenital limb contractures. "Mutations in GLE1 cause two recessive subtypes of arthrogryposis multiplex congenita (AMC), a condition characterized by joint contractures at birth." (PMID 39080077, 2024).
Huntington disease (1 paper, 2018). Huntington disease (HD) is a rare neurodegenerative disorder of the central nervous system characterized by unwanted choreatic movements, behavioral and psychiatric disturbances and dementia. "Several human diseases have been linked to Gle1 dysfunction, including ALS, Huntington’s disease, and the related disorders LCCS1 and LAAHD, which lead to spinal cord motor neuron atrophy and premature death, often prior to birth." (PMID 29899397, 2018).
Parkinson disease (1 paper, 2018). A progressive degenerative disorder of the central nervous system characterized by loss of dopamine producing neurons in the substantia nigra and the presence of Lewy bodies in the substantia nigra and locus coeruleus. "NUPL2 (ranked 7), a nucleoporin-like protein interacts with Gle1, functions in CRM1-mediated RNA export and is a risk locus for Parkinson’s disease." (PMID 29134320, 2018).
cancer (2 papers, 2024). A tumor composed of atypical neoplastic, often pleomorphic cells that invade other tissues. "Mutations in GLE1 can lead to developmental and neurodegenerative disorders and some cancers." (PMID 38504158, 2024). "HepG2 cells were resistant to the GLE1 extract, while doses greater than 300 μg/mL were toxic to most of the cancer cells." (PMID 38268969, 2024). "All the cancer cells were more susceptible to the GLE-CF-SF extract compared to GLE1 and GLE1-CF." (PMID 38268969, 2024).
neurodegenerative disease (2 papers, 2018 to 2020). A disorder of the central nervous system characterized by gradual and progressive loss of neural tissue and neurologic function. "Several studies show that the mutation of GLE1 is related to neurodegenerative diseases." (PMID 29746542, 2018). "The catastrophic effects of the lethal gle1-Finmajor mutation are linked to perturbations of Gle1 oligomerization, and likewise, altered Gle1 oligomerization might also contribute to defects in SG biology and mRNP metabolism that are associated with neurodegenerative disease." (PMID 32981894, 2020). "GLE1 is the responsible gene for LCCS1, a fetal neurodegenerative disease." (PMID 29746542, 2018). "In this study, we confirmed that GLE1 knock-down reduces the cytoplasmic mRNA expression of some genes, like FUS and HDAC1, which participate in neurodegenerative disease." (PMID 29746542, 2018). "We were interested in the finding that GLE1 showed a relation with neurodegenerative diseases but DBP5 and IP6 were not related to them." (PMID 29746542, 2018). "Taking our findings together with previous findings, it might be possible to explain why GLE1 only has a relation with neurodegenerative diseases but DBP5 and IP6 are not related to them." (PMID 29746542, 2018).
neurologic disorders (1 paper, 2025). "Specifically, mutations in GLE1 are associated with developmental and neurologic disorders." (PMID 40674274, 2025).
GLE1 also shares sentences with these, for which no sentence is quoted: genetic disease (2 papers); lethal congenital contracture syndrome (2); congenital arthrogryposis with anterior horn cell disease (1); hydrops (1); infection (1); macrosomia (1); multiple myeloma (1); uterine cancer (1).